PDC (phosducin)
Diseases named in the same sentence as PDC in open-access papers (continued):
Sharing a sentence is not in itself a finding about the gene and the disease.
tumor (continued). "With cDC1 known to support anti-tumor responses and pDC involved in viral pathogen defense, these results align with previous findings that a higher cDC1/pDC ratio correlates with better anti-PD1 responsiveness." (PMID 39095793, 2024). "By their unique expression of CD317 (PDCA-1) we identified a minor population [0.04%( ± 0.02%)] of all leukocytes) of pDC in the tumor tissue." (PMID 38500875, 2024). "For example, pDC can act to elicit enhanced anti-tumor immunity via production of type I interferons (IFN-I)." (PMID 38619620, 2024). "The effect of PDc on tumour-induced angiogenesis was evaluated in vivo using a chick yolk membrane (YSM) ex ovo assay." (PMID 37896150, 2023). "This reconstructs the structure of the PDC center and inhibits PDC activity, further promoting tumor cell proliferation and growth." (PMID 37143582, 2023). "There is pDC accumulation in blood, tumor tissue, and ascites in HCC patients, and high-density tumor infiltration of pDC is related to poor outcomes." (PMID 38074100, 2023). "Little research has directly investigated the variations in pDC-tumor cell crosstalk across diverse tumor types; therefore further studies are needed to understand pDC biology." (PMID 37817484, 2023). "PDc impaired the ability of HepG2 cells to migrate, invade, and adhere, which are the prerequisites for tumour metastatic dissemination." (PMID 37896150, 2023). "Our results showed that ARHGAP expression was negatively correlated with pDC infiltration in the CCA tumor microenvironment." (PMID 36676763, 2023). "These tumor-infiltrating DC (cDC1, cDC2, pDC, mregDC, MoDCs) states are conserved across solid human cancer types." (PMID 36275666, 2022). "Our past understanding of pDC biology is that they are specialized effectors of anti-viral and anti-tumor immunity." (PMID 36407322, 2022). "CXCL12 neutralization abolished the 7HP349 treatment–related increase in frequencies of CD8+ and CD4+ Teffs and tumor myeloid cell infiltrates consisting of IMs, granulocytes, M1 macrophages, M2 macrophages, pDC, and cDC2." (PMID 35552271, 2022). "More important, survival analysis of 122 OSCC patients demonstrated that increased tumor-infiltrating pDC was a strong predictor of poor outcome (P = 0.0095)." (PMID 33854604, 2021). "Despite their theoretical capability of inducing strong anti-tumor T-cell responses and priming CD4+ and CD8+ T-cells against tumor antigens, pDC infiltration is found to be associated with poor prognosis in several solid tumors." (PMID 34483843, 2021). "Previously, we also demonstrated an increased frequency of tumor-infiltrating pDC in the primary OSCC microenvironment." (PMID 33854604, 2021). "We first evaluated the level of pDC infiltration in the paraffin-embedded tumor tissue sections of 122 OSCC patients using immunofluorescence." (PMID 33854604, 2021). "Conversely, purified TNF-α treatment resulted in enhanced NF-κB activity and CXCR-4 expression, which further suggests that TNF-α is an important mediator of tumor-infiltrating pDC in the promotion of tumor growth and metastasis." (PMID 33854604, 2021). "In the present study, we interestingly found that tumor-infiltrating pDC were highly present in OSCC tissues expressing high levels of CXCR-4." (PMID 33854604, 2021). "Despite the fact that their function within the context of the tumor microenvironment is still not fully known, future perspectives will improve our understanding of pDC responses in cancer patients." (PMID 34442012, 2021). "In 2017, we first reported that tumor-infiltrating pDC are closely related to LN metastasis in OSCC patients." (PMID 33854604, 2021). "Taken together, we confirmed that combination of TEW‐7197 and ramucirumab reduced tumor spheroid and GC PDC‐induced blood vessel formation concomitantly in the spheroid‐on‐a‐chip model." (PMID 34542244, 2021).
tumor (continued). "The present study shows that these impaired pDC in the pre-tumor microenvironment can also promote cancer cell proliferation and migration via NF-κB-activated CXCR-4 overexpression by a paracrine mechanism." (PMID 33854604, 2021). "Although a further study is required to authenticate such chemerin-induced infiltration of pDC in cancers, it is important to mention here that the tumor microenvironment modifies the tumor infiltrating pDC." (PMID 34588926, 2021). "In this study, we attempted to demonstrate the potential effect of ramucirumab and TGF‐β receptor inhibitor on tumor invasiveness and PDC‐induced angiogenesis in diffuse‐type GC cell line and PCD models." (PMID 34542244, 2021). "Tumor-induced down-regulation of TLR9 expression has been identified as one leading mechanism of pDC dysfunction within the tumor environment." (PMID 32054102, 2020). "It has been proposed that pDC functions are hijacked by the tumor microenvironment, but upon appropriate re-activation, they can be reprogrammed to anti-tumor functions." (PMID 32054102, 2020). "For example, pDC agonists such as imiquimod and R848 can activate and maintain immune response and improve tumor control." (PMID 33198125, 2020). "Tryptophan is another amino acid critical to antitumor T cell function, and IDO‐1 expression by tumor‐associated MDSC and regulatory pDC is a frequently reported mechanism of tumor immune escape." (PMID 32508018, 2020). "Lactate has been recently proposed as an inhibitor of the pDC function in the tumor microenvironment." (PMID 32731406, 2020). "Several excellent reviews contributed by well-known experts in the field address antiviral and anti-tumor activities of pDC, as well as properties of oncolytic viruses." (PMID 31083559, 2019). "According to our previous study using the same tumor model, pDC, which can predominantly produce large amounts of IFN-I because of its high basal expression of IRF7, was the main producer of IFN-I in tumors." (PMID 31049360, 2019). "pDC dysfunction in the tumor microenvironment, however, remains a barrier to successful therapy and it is reported in some solid tumor models that intra-tumoral administration of CpG fails to reprogram the tolerogenic phenotype of tumor-associated pDC." (PMID 30979057, 2019). "The presence of mDC in blood had no impact on patients' outcome highlighting the specific pejorative role of pDC in the context of tumor microenvironment." (PMID 31777600, 2019). "It is well established that tumor-infiltrating pDC are poorly immunogenic and have a significantly impaired capacity to produce IFN-I." (PMID 30979057, 2019). "Most importantly, pDC cooperate with classical dendritic cells from the myeloid lineage in the anti-tumor defense." (PMID 31083559, 2019). "In a glioma mouse model, pDC depletion led to prolonged survival, decreased tumor-infiltrating Treg numbers, and substantially decreased production of IL-10 in the remaining intratumoral Tregs." (PMID 30987228, 2019). "The purpose of our review is not to repeat these findings but to specifically focus on the role of pDC in anti-tumor defenses in the context of oncolytic herpes simplex virus 1 (HSV-1)." (PMID 31083559, 2019). "In a cohort of 44 ovarian-cancer patients, pDC were the most abundant DC subset in tumor and malignant ascites, but they were almost depleted in peripheral blood." (PMID 30200478, 2018). "Drobits and co-workers showed that Imiquimod treatment promoted the secretion of both TRAIL and granzyme B resulting in pDC-mediated tumor killing." (PMID 29050360, 2017). "A possible explanation is that pDC frequencies are regulated by the tumour itself and that this regulation takes place very early in the metastatic process." (PMID 25592374, 2015).
tumor (continued). "The exact nature of the relationship between imiquimod treatment and pDC-dependent tumor clearance has yet to be defined; however several studies have shown that imiquimod is able to induce malignant cell apoptosis through TLR7/IFN-α-dependent pathways." (PMID 23606870, 2013). "In mice, imiquimod application (TLR7-L) or intratumoral injection of CpG (TLR9-L) reversed the functional inhibition of pDC, thereby promoting tumor regression." (PMID 20454561, 2010). "A deeper understanding of the mechanisms ruling type I IFN production and, more specifically, of pDC functional receptors, will be fundamental for planning new immune interventions for controlling autoimmune, viral and neoplastic diseases." (PMID 21151495, 2010). "Fluorescent labelling of the PDC confirmed high tumor specificity and accumulation." (PMID 40428099, 2025). "This highlights that pDC may have important roles both for sustaining and disrupting anti-tumor immunity in OSCC patients." (PMID 38954023, 2024). "This underscores the complexity of pDC functionality, which may manifest differently across various cancer types or tumor stages." (PMID 38927922, 2024). "Moreover, both CCL21 and tumor-triggered pDC activation can be blocked by either CCL21 or CCR7 antibody neutralization." (PMID 39456552, 2024). "In conclusion, despite encouraging evidence, more work is required to fully unravel the effects of IR engagement on pDC functions in specific tumor microenvironments and to uncover the beneficial role of therapeutic blockade of pDC-specific IRs in future immunotherapeutic strategies." (PMID 38504978, 2024). "We have previously published that pDC depletion in the diphtheria toxin receptor-mediated conditional knockout mouse model of GBM results in significantly increased overall survival of the tumor-bearing mice." (PMID 39456552, 2024). "Thus, pDC infiltration correlated positively with ICOS+ Treg infiltration in the tumor tissue of GC patients." (PMID 38927922, 2024). "In this cancer, pDC frequencies were significant lower in tumor tissue compared to normal mucosa." (PMID 38927922, 2024). "In this paper, the xCell algorithm was first used to calculate the cellular abundance of 64 types of immune cells and stromal cells in tumor samples from the TCGA database, and the high-abundance pDC group and cDC group were divided according to the results of a survival analysis." (PMID 36835467, 2023). "However, PDc reduced tumour growth compared to vehicle control group and single drug treated-groups." (PMID 37860118, 2023). "Among the CD11b+ myeloid cells, we identified cDCs and macrophages based on known markers that have been previously identified in human tumor-infiltrating immune cells, including tumor-associated dendritic cells (XCR1+ cDC1, SIRP1a+ cDC2, SiglecH+ pDC) and tumor-associated macrophages (TAMs)." (PMID 37055410, 2023). "Moreover, hypoxia promotes pDC recruitment to tumor tissues through the hypoxia-inducible factor 1α (HIF-1α)/SDF-1/CXCR4 pathway." (PMID 37817484, 2023). "Additionally, R848 induced expression of co-stimulatory molecules and chemokine receptor CCR7, which is involved in pDC recruitment to the tumor site." (PMID 38239354, 2023). "Furthermore, PDc inhibited the secretion of pro-angiogenic factors, reducing angiogenesis induced by tumour cells." (PMID 37896150, 2023). "In summary, lactate and adenosine accumulation and FAO suppression in the hypoxic TME of HNSCC might accelerate tumor growth by promoting pDC reprogramming." (PMID 34964283, 2022). "However, intratumoral administration of a TLR7 agonist induced pDC activation and inhibited tumor growth through modulation of Tregs." (PMID 35806328, 2022). "Among dendritic cells, the main differences were the expected high abundance of fDC in GC; an enrichment of cDC1 in Pos compared to both the NegTum and NegInPos; a higher density, but not proportion, of cDC1 in GC in comparison with Neg; and a general enrichment of pDC in the tumor compared to GC." (PMID 33842341, 2021).
tumor (continued). "In addition, the relationship between clinical features (tumor stage and age) and pDC abundance was explored." (PMID 33869191, 2021). "The ratio of cDC and pDC varies between peripheral blood, ascites and tumor sites." (PMID 33584699, 2020). "According to The most prominent subsets of DCs is pDC in ascites and tumor sites, while cDC is more than pDC in the peripheral blood, which suggests that peripheral blood could be a proper resource of the DCs for manufacturing." (PMID 33584699, 2020). "In ovarian cancer, for example, pDC accumulate in the tumor epithelium, but not in the ascites, and this is associated with early relapse." (PMID 30979057, 2019). "To further examine the role of monocytes and pDC for anti-tumor immunity, we repeated PBMC-CM toxicity, NK cell activation and degranulation assays, as well as T cell priming experiments but depleted CD14+ monocytes, pDC, or both, from the whole PBMC population." (PMID 31262361, 2019). "This dysfunction is mostly limited to pDC that are localized to the tumor microenvironment." (PMID 30979057, 2019). "Although type I IFNs play a critical role in anti-tumor immune response, previous studies have reported pDC dysfunction and acquisition of tolerogenic function in the tumor bed, thus providing evidence that cancer cells do adopt immunoregulatory strategies to evade intra-tumoral activation of pDCs." (PMID 31440253, 2019). "DDI treatment also robustly decreased the ability of PDC cells to form tumor sphere." (PMID 31633874, 2019). "Furthermore, tumor clearance was found to be directly dependent on the corresponding pDC infiltration, with a positive correlation present between pDC numbers and the degree of tumor regression." (PMID 23606870, 2013). "Finally, Jolanda De Vries group has recently completed the first phase I clinical trial by intranodal injection of tumor-antigen-loaded and -activated pDC in metastatic melanoma patients." (PMID 24832799, 2013). "These latter results will deserve further investigation since the ligand of NKp44, although still elusive, is known to be expressed on several cancer cell lines and might therefore impact on pDC function during the in vivo anti-tumor immune response." (PMID 21151495, 2010). "In addition to transcriptomic approaches, emerging experimental systems enabling selective pDC depletion (e.g., conditional pDC-knockout mouse models) may provide valuable functional confirmation of the role of pDCs in early tumor-immune interactions." (PMID 41375078, 2025). "However, IRs can be hijacked by pathogens or tumour cells, thus hindering pDC activation." (PMID 38504978, 2024). "The specific mechanisms of pDC–tumor cell crosstalk might contribute to this divergent effect." (PMID 37817484, 2023). "However, in a tumor environment, almost all pDC activity is suppressed by tumor-derived TGF-β." (PMID 35806328, 2022). "Furthermore, activation of pDCs has been shown to induce anti-tumor immunogenic responses and several pDC clinical trials have shown promising clinical benefits in human cancers, suggesting that pDCs could be employed to induce anti-tumor immunity." (PMID 35053338, 2022). "However, the functions of pDC in the TME are still controversial as to whether they are tumor-promoting or tumor-suppressive." (PMID 36275666, 2022). "However, the relationship between tumor-infiltrating pDC and LN metastasis is rarely reported." (PMID 33854604, 2021). "However, the role of the pDC is different among different tumor types." (PMID 33869191, 2021). "However, iDC was significantly lower in tumor tissues but pDC and aDC were significantly higher." (PMID 32728493, 2020). "Furthermore, the capacity of pDC to induce T cell tolerance can promote tumor expansion." (PMID 30979057, 2019).
tumor (continued). "Direct correlation analysis with estimated tumor immune infiltrates also revealed for several cancer types positive association of LTR21B and MER57F to tumor plasma dendric cell (pDC) expression, which is consistent with known biological function of pDC as a potent producer of type I IFN." (PMID 31745090, 2019). "Such cases have to consider, during the design process, the microenvironment that the assembled PDC is to be located, since different enzymes and/or the tumor microenvironment might trigger the improper release of the drug from the PDC, i.e., to end up with the drug-carrying part of the linker." (PMID 29765474, 2018). "The presence of pDC in the tumor only (but not in ascites) was associated with early relapse." (PMID 30200478, 2018). "To investigate the efficacy of co-treatment with the SCARB1 inhibitor BLT-1 and TMZ on tumor recurrence after TMZ treatment, we used PDC, PDO, and PDX from the same patient." (PMID 41390817, 2025). "Regarding the expression of additional surface proteins, especially tumor-infiltrated and to a lesser extent ascites-derived pDC expressed ICOS-L, CD86, and CD40 indicating higher pDC activity in OC tissue." (PMID 41221283, 2025). "Only two pRCC PDC (300 and 195) showed a discrepancy between the tumour and the cell culture: while the NQO1 mRNA level and activity in the tumour were downregulated compared to the normal, the PDC showed increased NQO1 activity." (PMID 39707614, 2025). "Thus, timing and duration of pDC activation may represent critical parameters in antitumor immune responses, requiring to be thoroughly understood and tightly regulated depending on the specific tumor context." (PMID 38504978, 2024). "Further dissecting the overall mechanism of pDC-mediated GBM immunosuppression, in this study, we identified CCL21 as highly upregulated by multiple GBM cell lines, which recruit pDCs to tumor sites via CCL21-CCR7 signaling." (PMID 39456552, 2024). "pDC is a DC subgroup that secretes a high level of type I IFN after stimulation by toll-like receptors (TLRs), which results in the existence of anti-tumor effects of pDC in TME." (PMID 38279145, 2024). "pDC are characterized by their ability to produce large amounts of type I interferon (IFN-I) upon viral infection, yet their role in anti-tumor immunity remains to be fully explored." (PMID 38500875, 2024). "In line with this, tumor cells expressing ligands engaging IRs such as BDCA-2, ILT7, TIM3 and CD44 block pDC activation, while this blocking is prevented when IR engagement or signaling is inhibited." (PMID 38504978, 2024). "A high expression level of YBX3 was significantly correlated with the tumor pathological stage, histological grade, TNM stage, and the abundance of aDC, pDC, Th1, and Treg immune cells." (PMID 37418046, 2023). "Thus, we suggest that NN with PDc may be a true neoplastic lesion, and PDc especially seems to be a component of neoplasia possessing malignant characteristics, such as defective DDR with a high proliferative capability, which is a phenotype of genomic instability during follicular carcinogenesis." (PMID 35892838, 2022). "Second, we defined a 21-gene tumor cDC2 subset-specific signature by comparison with blood cDC2 and tumor MMAC, CD14+ DC and pDC." (PMID 35418195, 2022). "Accordingly, we show that intratumoral injection of frOpn1 mediates pDC recruitment and activation to express high levels of IFN-β restricting tumor growth." (PMID 35878016, 2022). "Another study reported that combined cDC2 and pDC administration resulted in increased frequencies and IFN-γ production of tumor-reactive T cells in an OVA-specific tumor model." (PMID 33796917, 2021). "cDC1s are critical for eliciting anti-tumor CD8+ T cell responses and T helper 1 (TH1) responses, cDC2 for CD4+ T cell response, and pDC for producing large amounts of type I IFN." (PMID 33648605, 2021).